SERPINA3 (serpin family A member 3)
Diseases named in the same sentence as SERPINA3 in open-access papers (continued):
Sharing a sentence is not in itself a finding about the gene and the disease.
Pca (1 paper, 2025). "When examining the association between SERPINA3 expression and the survival of patients with PCa, we found in the Gene Expression Profiling Interactive Analysis database that low expression of SERPINA3 may significantly reduce patient survival rates." (PMID 40367014, 2025). "Verifying the expression of SERPINA3 in hormone-sensitive and CRPC samples in the human PCa datasets, it was revealed that SERPINA3 expression was significantly downregulated in CRPC samples in Michigan 2012 and Cambridge datasets." (PMID 40367014, 2025). "In bone metastases of PCa, overexpression of SERPINA3 has been detected via hematoxylin and eosin staining, leading to enhanced osteogenic differentiation." (PMID 40367014, 2025). "It was also confirmed in collected clinical tissue samples of patients with PCa and varying Gleason scores that the expression of SERPINA3 decreased with increasing Gleason score." (PMID 40367014, 2025). "These experimental results indicated that SERPINA3 inhibited the progression of PCa by promoting the recruitment and M1 polarization of macrophages." (PMID 40367014, 2025). "SERPINA3 serves a crucial role in inhibiting the progression of PCa." (PMID 40367014, 2025). "These experimental results indicated that overexpression of SERPINA3 may significantly inhibit the proliferation, invasion, and migration of PCa." (PMID 40367014, 2025). "Furthermore, downregulation of SERPINA3 expression in CRPC was detected compared within hormone-sensitive PCa." (PMID 40367014, 2025). "Similarly, the expression of SERPINA3 in hormone-sensitive PCa cell lines LNCAP was significantly upregulated compared with that in CRPC cell lines (VCAP, C4-2B, PC3, and DU145)." (PMID 40367014, 2025). "Notably, the impact of SERPINA3 expression on the progression of PCa remains to be fully elucidated." (PMID 40367014, 2025). "Similarly, the MSKCC and Michigan PCa datasets showed that low expression of SERPINA3 significantly reduced the overall survival of patients with PCa." (PMID 40367014, 2025). "Interestingly, as SERPINA3 functions as a plasma protease, it may also serve as a potential biomarker for blood-based detection of PCa, enabling precise monitoring of tumor progression and postoperative recurrence in patients with PCa." (PMID 40367014, 2025). "Therefore, the correlation of SERPINA3 and CXCL2 expression with M1/M2 polarized macrophage infiltration in PCa was validated using QUANTISEQ methods in the Timer2.0 tumor immune infiltration-related database." (PMID 40367014, 2025). "Similarly, the expression of SERPINA3 was confirmed to be negatively correlated with Gleason score in both the MSKCC and Cambridge PCa datasets." (PMID 40367014, 2025). "Furthermore, the Michigan 2012 PCa dataset confirmed that the expression of SERPINA3 in tissues of patients with metastatic PCa was significantly lower than that of normal patients and those with non-metastatic PCa." (PMID 40367014, 2025). "In addition, the UALCAN, which covered TCGA data of patients with PCa, verified the negative relationship between SERPINA3 expression and Gleason score." (PMID 40367014, 2025). "The present study hypothesized that SERPINA3 may activate the IL-17 and TNFα signaling pathways by influencing the expression of CXCL2, thereby affecting the recruitment of M1 macrophages and inhibiting PCa progression." (PMID 40367014, 2025). "However, the functional role of SERPINA3 in PCa has not been extensively investigated." (PMID 40367014, 2025).
phospholipidosis (1 paper, 2024). "Additionally, the downregulation of FABP1, HPN, and SERPINA3 genes is related to phospholipidosis." (PMID 38992651, 2024).
psoriasis (1 paper, 2022). An autoimmune condition characterized by red, well-delineated plaques with silvery scales that are usually on the extensor surfaces and scalp. "Recombinant SerpinA3 alleviated the severe inflammation in the IMQ-induced psoriasis-like mouse model." (PMID 35864103, 2022).
pustular psoriasis (1 paper, 2023). "Other genes involved in pustular psoriasis are SERPINA1 and SERPINA3 (serine protease inhibitors that inhibit cathepsin G, neutrophil elastase, and proteinase 3), TNIP1 and IL1RN." (PMID 37628670, 2023).
sporadic Creutzfeldt-Jakob disease (1 paper, 2022). A rare sporadic human prion disease characterized by rapidly progressive cognitive impairment in combination with variable neurologic signs and symptoms including myoclonus, visual or cerebellar problems, pyramidal or extrapyramidal features, or akinetic mutism. "SERPINA3 upregulation has already been observed in the CNS of sporadic Creutzfeldt-Jakob disease (sCJD) patients, while cerebrospinal fluid (CSF) and urine samples from these patients also revealed high level of SERPINA3 protein." (PMID 35416570, 2022).
steatosis (1 paper, 2024). Increased lipid within the cytoplasm of cells. "To further discuss the potential role of the core genes RPS6KA1 and SERPINA3 in steatosis, NASH and AS, we analyzed pathways associated with a single gene using GSEA-KEGG." (PMID 38606153, 2024). "Therefore, we selected the RPS6KA1 and LMCD1 genes as diagnostic for steatosis and AS, and the RPS6KA1 SYNP02, JAML and SERPINA3 genes as diagnostic for NASH and AS." (PMID 38606153, 2024). "We found differential expression of RPS6KA1 in patients with steatosis and NASH, and of SERPINA3 only in those with NASH compared with normal individuals." (PMID 38606153, 2024). "This is consistent with our findings of significantly reduced SERPINA3 expression in NASH in GSE89632, GSE48452, GSE58979 NAFLD datasets but did not significantly change in steatosis." (PMID 38606153, 2024).
syphilis (1 paper, 2024). A contagious bacterial infection caused by the spirochete Treponema pallidum. "Using multicenter ELISA validations, we selected three biomarkers (SEMA7A, SERPINA3, and ITIH4) and confirmed their efficacy in distinguishing NS from syphilis and other brain diseases, including infectious diseases." (PMID 38380496, 2024).
temporal lobe epilepsy (1 paper, 2024). A localization-related (focal) form of epilepsy characterized by recurrent seizures that arise from foci within the temporal lobe, most commonly from its mesial aspect. "Several apolipoproteins (APOA1, APOD, and APOA4), serpin protease inhibitors (SERPINA3, SERPINF1, etc.), complement components (C9, C8, and C1R), and a total of 42 proteins were found to be significantly upregulated in the temporal lobe epilepsy group." (PMID 39063177, 2024).
thrombosis (1 paper, 2025). "Coagulation-related factors, such as F2, SERPIND1, SERPINF2, SERPINA3, FGA, FGB, and FGG, are also downregulated, leading to coagulation dysfunction in the body, which is not conducive to post-exercise recovery and can even lead to thrombosis in severe cases." (PMID 40646880, 2025).
variant Creutzfeldt-Jakob disease (1 paper, 2022). A form of Creutzfeldt-Jakob disease that is most commonly contracted after consuming meat from an animal suffering from bovine spongiform encephalopathy. "In 2014, a microarray-based gene expression study revealed the upregulation of SERPINA3 transcript in brains from bovine spongiform encephalopathy (BSE)–infected cynomolgus macaques, which are considered a highly relevant model for variant Creutzfeldt-Jakob disease (vCJD)." (PMID 35416570, 2022).
tumor (62 papers, 2006 to 2026). "It has been reported that Serpin peptidase inhibitor clade A member 3 (SERPINA3) is associated with the mobility and invasion of tumor cells." (PMID 34449972, 2021). "Recent studies have indicated that serpin peptidase inhibitor, clade A, member 3 (SERPINA3) is a potential marker associated with tumor progression, which connoted that SERPINA3 is related to malignant phenotypes in cancer." (PMID 33569740, 2021). "It is reported that SERPINA3 expression in cancer tissue is lower, where a high activity of relevant proteinases is linked to tumor growth, metastasis and aggressiveness." (PMID 29069770, 2017). "Furthermore, SerpinA3 has been implicated in tumour invasiveness and increased epithelial to mesenchymal transition (EMT) via regulation of EMT markers E-cadherin, N-cadherin vimentin and EZH2 in an in-vitro model of triple-negative breast cancers." (PMID 39340596, 2024). "It appears that higher expression of the SERPINA3 protein may cause more aggressive tumor biology due to the remodeling of the extracellular tissue matrix." (PMID 36672665, 2023). "On the other hand, a lower amount of SERPINA3 protein should lead to a decrease in the amount of NF-κβ and cell apoptosis, thus inhibiting tumor growth." (PMID 40672945, 2025). "We established a stable cell line overexpressing SERPINA3 in PC3 cells and validated the function of SERPINA3 through cell cloning, invasion, migration assays, and subcutaneous tumor experiments." (PMID 40367014, 2025). "In the present study on SERPINA3, it was discovered that its antitumor effect was primarily achieved through the recruitment of numerous M1 macrophages into the tumor microenvironment, which represents a novel viewpoint." (PMID 40367014, 2025). "The results indicated that the tumor proliferation ability of mice in the SERPINA3-overexpressing group was significantly weakened." (PMID 40367014, 2025). "Following tumor transplantation, mice overexpressing SERPINA3 exhibited significantly reduced tumor volume growth and final tumor weight." (PMID 40367014, 2025). "We further validated that the representative core genes in the IL-6/JAK/STAT3 pathway (Il6st (Gp130), Fas and Stat1) and the late response of estrogen (St6gal, Areg and Serpina3) were highly reduced in shMCT-1 tumor when compared to scramble tumor." (PMID 38505617, 2024). "The tumor-stroma interactions at the leptomeninges activate tumor-promoting signaling, mediated through upregulation of SERPINA3." (PMID 38866016, 2024). "After categorizing the distances of tumor spots to the stroma compartment, we observed that the median expression of SERPINA3 in the leptomeningeal samples was significantly higher (p < 0.05) within the 2,000 μM proximal to stroma than at larger distances." (PMID 38866016, 2024). "In MI and LV hypertrophy in ATF3-transgenic mice models with tumors, an enhancement in tumor growth and an increase in cardiac expression of SerpinA3 were observed." (PMID 38279150, 2024). "Knocking down SERPINA3 or inhibiting the downstream IGR1R/PI3K/AKT axis results in tumor cell death and re-sensitization to MAPK-targeting therapy." (PMID 38866016, 2024). "Here, we show that meningeal cell-induced SERPINA3 expression at the tumor/stroma interface promotes the amplification of PI3K/AKT signaling and the reactivation of ERK in the tumor cells, thereby overcoming BRAF/MEK inhibition." (PMID 38866016, 2024). "In summary, it has been reported that SerpinA3 is upregulated in association with various types of CVD and enhanced tumor proliferation and invasiveness in several types of cancer." (PMID 38279150, 2024). "SERPINA3 appears to exhibit cancer- and location-specific biological roles, functioning as either a facilitator or inhibitor of tumor growth in various types of cancer." (PMID 38087342, 2023).
tumor (continued). "Consistent with previous studies, our data also showed that SERPINA3 expression was abnormally elevated in both tumor tissue and stool samples from CRC patients, indicating its diagnostic ability for CRC." (PMID 37313408, 2023). "During tumor progression, STAT3-dependent SERPINA3 enhances tumor cell invasion, migration, and angiogenesis." (PMID 37313408, 2023). "SERPINA3 promotes tumor development by regulating the transcription of some oncogenes, for example in hepatocellular carcinoma, by increasing the length of telomeres, cell proliferation, and migration." (PMID 36672665, 2023). "We used qRT-PCR to measure the relative mRNA expression levels of four risk genes (TIPARP, SERPINA3, MT1M, and CST2) in the normal prostate tissue cell RWPE-1 and in different tumor cell states such as LNCaP and C4-2 cell lines." (PMID 37346077, 2023). "Through two independent validation cohorts, we finally identified five fecal tumor immune-related proteins (CAT, LTF, MMP9, RBP4, and SERPINA3) as well as a biomarker panel that had definite diagnostic value for CRC." (PMID 37313408, 2023). "Similar to the confirmation of the mechanism by which HOXA-AS2 regulated GBM cell tumor growth, The miR-2116-3p inhibitor and si-SERPINA3 were co-transfected into U251 and A172." (PMID 35387643, 2022). "The mRNA expression of selected genes including SERPINA3 from microarray data were validated in the tumor core and peritumoral brain zone." (PMID 34445646, 2021). "Previous studies have shown that SERPINA3 plays an important role in cytokinesis, proliferation, apoptosis, and tumour metastasis." (PMID 34449972, 2021). "It is possible that the presence of other cytokines in the CSF, highlighting here a crucial role for the inflammatory response, can sustain the overexpression of SERPINA3, among other genes, and together concert the buildup of a tumor supportive environment." (PMID 33747938, 2021). "SERPINA3 protein expression was higher in peritumoral brain zone compared to tumor core and also was higher in older patients and IDH wild type and recurrent tumors." (PMID 34445646, 2021). "Albeit its protein product alpha-1-antichymotrypsin has unclear functions, the SERPINA3 gene knockdown in vitro caused decreased HGG tumor cell proliferation, invasion, migration, transition to mesenchymal phenotype, stemness, and radioresistance." (PMID 34445646, 2021). "SERPINA3 is one of the ccB phenotype genes in ClearCode34, which is specific for more aggressive and metastatic ccRCC tumor subtypes." (PMID 34572331, 2021). "Osteopontin (OPN; SPP1) and two proteins of the serpin family, such as SERPINA1 and SERPINA3, were those with higher expression in the P3 subtype compared to the rest of tumours." (PMID 31560832, 2019). "As one of the most abundant serpins in human plasma, SERPINA3 has shown overexpression in many types of tumor." (PMID 27213583, 2017). "We found that the L1CAM, TSPAN3 and SERPINA3 gene expression were significantly up-regulated in M than Wt sporadic tumor samples, whereas COL1A1 and MAT2A mRNA showed similar levels in both groups." (PMID 28418912, 2017). "In addition, overexpression of SERPINA3 has been also widely reported to promote tumor invasion and migration, epithelial-mesenchymal-transition, further accelerate tumor progression and evolution." (PMID 41550507, 2026). "Additionally, in vitro experiments were designed to validate the relationship between SERPINA3 expression in tumor cells, and the recruitment and polarization of macrophages." (PMID 40367014, 2025). "Colony formation, transwell assays, and subcutaneous tumor formation experiments in mice demonstrated that overexpression of SERPINA3 may significantly inhibit the proliferation and invasion of PC3 cells." (PMID 40367014, 2025).
tumor (continued). "We could hypothesize that the decline in SERPINA3 observed is due to a treatment response with tumour decline, in patients with CTRCD this decline might be counteracted by an increase, caused by CTRCD, but this is still purely speculative." (PMID 40087712, 2025). "The in vivo experiments reinforced the conclusions drawn from the cell experiments, demonstrating that overexpression of SERPINA3 could inhibit tumor proliferation." (PMID 40367014, 2025). "This study identifies a tumor-promoting role of meningeal stroma, mediated through SERPINA3." (PMID 38866016, 2024). "This evidence suggests that SerpinA3 from CVD could be a cardiokine responsible for the enhanced tumor growth." (PMID 38279150, 2024). "Moreover, after searching the immunohistochemistry (IHC) staining results, the pictures for CST2 and SERPINA3 in normal and tumor tissues in the HPA database were similar." (PMID 37346077, 2023). "Here, we show the osteogenic and tumor‐suppressive roles of SERPINA3 and LCN2 in BPCa." (PMID 37408474, 2023). "Interestingly, SERPINA3 was positively correlated with TNF and TNF was positively correlated with CCL2, a marker of tumor associated macrophages." (PMID 36406134, 2022). "Furthermore, heart tissue of patients with HF can secrete a large amount of serpinA3 by itself, further increasing the intestinal tumor burden in mice." (PMID 33401250, 2020). "Although SERPINA3 has been shown to present in multiple tumors, its functional impact on tumor progression remains largely unknown." (PMID 27213583, 2017). "However, increasing evidence suggests that SERPINA3/Serpina3c also plays an equally important role in non-tumour contexts, and the mechanism of action, especially in neurodegenerative diseases, cardiovascular diseases, and metabolic disorders, deserves to be investigated in depth." (PMID 40076571, 2025). "Notably, SerpinA3 has been implicated as an acute phase protein during immune reactions in CVD, neurological diseases and as mediator of both cancer progression and immune suppression in the tumor microenvironment." (PMID 39340596, 2024). "We next determined whether SERPINA3 promotes breast stromal tumor cell invasion." (PMID 33569740, 2021). "High tumor-intrinsic expression of NOTUM, NKD1, and SERPINA3, together with elevated CD8+ T cell infiltration and a reduced Treg/CD3+ ratio within the TME, robustly associated with major pathological response (MPR)." (PMID 42220510, 2026). "Using bioinformatics techniques, we conducted in-depth analysis and validation of the relationship between SERPINA3 and CXCL2 in the tumor microenvironment, elucidating their role in macrophages." (PMID 40367014, 2025). "The SerpinA3, PON1, and CP expression also remained unchanged in both the cardiac tissues and tumor in this model." (PMID 38279150, 2024). "Gain‐of‐function experiments of SERPINA3 and LCN2 in the horizontal co‐culture system and NICO‐1 and mouse xenograft experiments showed osteogenic and tumor‐suppressive roles in PCa." (PMID 37408474, 2023). "Moreover, HF was shown to associate with enhanced tumor growth, which may be independent of hemodynamic impairment but probably is caused by factors of cardiac origin (e.g. serpinA3)." (PMID 36698216, 2023). "Our in vitro experiments showed that SERPINA3 and LCN2 suppressed the proliferation of BPCa cells, suggesting that these two genes are tumor suppressors in BPCa; TCGA dataset analysis supported this conclusion." (PMID 37408474, 2023). "Thus, as SERPINA3 is known to inhibit mast cell chymase, SERPINA3 may act as a tumor suppressor." (PMID 37408474, 2023). "According to the qRT-PCR results, expression levels of NRP1, IGF2R, SERPINA3 and TNF were significantly upregulated in the comparison between in situ tumor samples and normal tissues in our clinical center." (PMID 36406134, 2022).